MMP2 (matrix metallopeptidase 2)
Diseases named in the same sentence as MMP2 in open-access papers (continued):
Sharing a sentence is not in itself a finding about the gene and the disease.
meningioma (12 papers, 2000 to 2024). A generally slow growing tumor attached to the dura mater. "Our previous report demonstrated that siRNA-induced CLIC2 knockdown in meningioma cells causes increased MMP-2 expression." (PMID 36672037, 2022). "Additionally, tissue inhibitors of metalloproteinases are also expressed in canine meningioma and is highest in papillary subtypes where it and a similar increase in MMP-2 expression may be associated with the more aggressive phenotype seen in this subtype." (PMID 31788444, 2019). "Of interest was our finding of high MMP2 expression in the meningioma group among all brain samples." (PMID 38474106, 2024). "We observed an increase in MMP2 mRNA levels in meningiomas compared to healthy samples, where MMP1 and MMP13 expression was not amplified in the control group." (PMID 38474106, 2024). "Previous studies focused on the role of MMP2 in meningiomas with tumor recurrence and brain invasion, and produced contradictory results." (PMID 35847854, 2022). "A similar correlation was also reported in our previous work with meningioma cells, where MMP-2 expression and cellular invasion were suppressed by the addition of recombinant CLIC2." (PMID 36672037, 2022). "In meningiomas, the protein levels of MMP1, MMP2, and MMP3 were similar to controls, but a slight decrease in MMP8 protein levels was identified." (PMID 38474106, 2024). "Other studies reported the important role of matrix metalloproteinases MMP-2 and MMP-9 in canine and human meningiomas, where they are involved in extracellular matrix degradation, required for tumor progression and recurrence." (PMID 38137885, 2023). "We noticed that genes such as TGFBI, SNAI1, MMP2, TGFB1, TGFB2, IGFBP7, and LTBP2 were upregulated by the treatment of M2-MDEs in meningioma cells and may contribute to tumor invasion and proliferation behavior." (PMID 35637794, 2022). "MMP-2 and - 9 are widely expressed in canine meningioma; however, expression is not correlated with peritumoral edema." (PMID 31788444, 2019). "They concluded that MMP-2 and MMP-9 expression by tumor cells, evaluated through immunohistochemistry, is not predictive of the formation of peritumoral edema in canine rostrotentorial meningiomas." (PMID 25821815, 2015).
myocardial ischemia (12 papers, 2009 to 2026). A disorder of cardiac function caused by insufficient blood flow to the muscle tissue of the heart. "In contrast, a previous study demonstrated that the metalloproteinase-2 (MMP-2) matrix degrades titin after 10 min of reperfusion in a rat myocardial ischemia/reperfusion injury model." (PMID 38203744, 2024). "The role of MMP-2 in the development of cardiac injury and dysfunction has clearly been demonstrated in animal models of cardiac ischemia, transgenic models that overexpress MMP-2, and knockout models for this protease." (PMID 35893744, 2022). "Among several cardioprotective drug targets, the participation of MMP-2 in the development of reperfusion injury following extended myocardial ischemia was clearly demonstrated in the early 2000s." (PMID 32977437, 2020). "In the setting of myocardial ischemia/reperfusion, acutely elevated MMP-2 activity contributes to myocardial stunning in human and rat hearts, independent of an effect on the ECM." (PMID 21450068, 2011). "However, Doxy (submicrobial doses) has been shown to significantly reduce cardiac MMP-2 activity in the clinical trial in patients undergoing artery bypass graft surgery with cardiopulmonary bypass (cardiac ischemia/reperfusion injury)." (PMID 32336955, 2020). "Schulz and colleagues showed that MMP-2 is activated and thereby degrades myocardial contractile proteins such as myosin light chain, titin and troponins, as well as sarcoplasmic/ endoplasmic reticulum Ca2+ ATPase 2a (SERCA2a) and junctophilin-2 during myocardial ischemia/reperfusion injury." (PMID 32977437, 2020). "Myocardial ischemia significantly increased the mRNA and protein expressions of IL-6, IL-8, TNFα, TGF-β1, MMP2, MMP9, and c-Myc in cMSCs." (PMID 36056383, 2022).
pancreatic ductal adenocarcinoma (12 papers, 2014 to 2025). An infiltrating adenocarcinoma that arises from the epithelial cells of the pancreas. "Notch3 also induces the formation of metastatic foci in pancreatic ductal adenocarcinoma cells through MMP2 (Matrix Metalloproteinase 2) and MMP9 (Matrix Metalloproteinase 9)." (PMID 38782818, 2024). "Verteporfin, an FDA-approved photosensitizer, that has been clinically used for the treatment of age-related macular degeneration, was recently found to suppress VM in pancreatic ductal adenocarcinoma by inhibiting MMP-2, VE-cadherin, and a-SMA expression." (PMID 31772665, 2019). "Additionally, YY1 has been shown to inhibit pancreatic ductal adenocarcinoma progression by suppressing MMP2 expression." (PMID 37724907, 2023). "Furthermore, it has been reported that the overexpression of EPHA2 upregulates the expression of MMP-2 in Capan2 pancreatic ductal adenocarcinoma cells." (PMID 24932309, 2014). "It is also overexpressed in pancreatic ductal adenocarcinoma (PDAC), where its deletion reduces cell migration and invasion by downregulating MMP-2 and MMP-14." (PMID 39768218, 2024). "A recent study showed that combined treatment of a MAPK inhibitor (Trametinib) and Palbociclib induced senescence and these senescent pancreatic ductal adenocarcinoma cells showed increased secretion of pro‐angiogenic factors (VEGF, PDGFA/B, and FGF2) and MMPs (MMP2/3/7/9/10)." (PMID 37854019, 2024). "Silenced YY1 promotes cell migration and invasion in pancreatic ductal adenocarcinoma by binding to the promoter region of Feline sarcoma-related (FER) and regulating signal transducer and activator of transcription 3 (STAT3)/matrix metallopeptidase 2 (MMP2) signaling pathway." (PMID 34818994, 2021). "In addition to ACY-241, although the mechanism is unclear, JQ1 downregulates the expression of MMP2- and MMP-9 and inhibits angiogenesis in glioblastoma tumors and pancreatic ductal adenocarcinoma cells." (PMID 32961679, 2020).
pituitary adenomas (12 papers, 2009 to 2025). "The overexpressed DDR1 protein further increased the expression of MMP-2/9 which caused haemorrhagic/infarction of the pituitary adenoma." (PMID 29615979, 2018). "It is worth mentioning that the PTTG can upregulate the expression and secretion of MMP-2 in HEK293 cells, MMP-2 is capable of inducing invasiveness in pituitary adenomas." (PMID 30733705, 2019). "Research also shows an obvious increase of β3GNT8 expression in invasive pituitary adenoma, and during the invasive growth of pituitary adenoma, β3GNT8, HG-CD147, and MMP-2 collectively increase the invasion of pituitary adenoma." (PMID 37771444, 2023). "Matrix metalloproteinase family members, primarily MMP-2 and MMP-9, have been well-recognized as core molecules responsible for the invasion of pituitary adenomas by our previous studied and other studies." (PMID 35463323, 2022). "The major types of MMPs involved in pituitary adenoma invasion can be classified into collagenases (MMP-1), gelatinases (MMP-2 and MMP-9), stromelysins (MMP-3), and membrane type (MMP-14) according to their function and location." (PMID 30733705, 2019). "Multiple studies have demonstrated significantly higher expression of MMP-9 and/or MMP-2, among others, in invasive pituitary adenoma compared to non-invasive tumors." (PMID 41206839, 2025). "Importantly, the knockdown of β-Catenin inhibited pituitary adenoma cell proliferation and migration probably by inhibiting AKT, STAT3, Cyclin D1, CDK4, MMP-2, and MMP-9." (PMID 35928898, 2022). "The study pointed out that hypoxia-inducible factor-1α, pituitary tumor transforming gene, vascular endothelial growth factor, fibroblast growth factor-2, and matrix metalloproteinases (MMPs, mainly MMP-2, and MMP-9) are core molecules responsible for the invasiveness of pituitary adenomas." (PMID 30733705, 2019). "MMP-2 mRNA expression was also intense in invasive pituitary adenomas and was significantly higher in invasive pituitary adenomas than those without invasion (68.2 ± 15.3; 21.8 ± 8.2; p < 0.05)." (PMID 27051552, 2016). "This retrospective cohort study aimed to study the expression of tumoral biomarkers (CTSK, MMP9, MMP2, TIMP2, and PTTG1) and evaluate their clinical significance in non-functioning pituitary adenomas (NFPAs) with different invasion patterns." (PMID 36052250, 2022).
pterygium (12 papers, 2011 to 2025). A wedge-shaped fibrovascular lesion arising from the bulbar conjunctiva and extending to the cornea. "Selective inhibitors of MMP-2, -9, and -14 are being explored as potential options for pterygium therapy." (PMID 40565017, 2025). "The expression of MMP1, an important factor in corneal collagen degradation, in pterygium head fibroblasts is higher than that in the body and conjunctiva, which creates conditions for degradation of the exposed elastic layer by MMP2." (PMID 33790949, 2021). "MMP3 was the only MMP/TIMP gene upregulated in pterygium, and only modestly, while MMP2, MMP7, MMP10, and MMP25 were downregulated." (PMID 34769520, 2021). "This DNA methylation pattern was consistent with reduced levels of TGM-2, as well as increased levels of MMP-2 and CD24 proteins, contributing to fibroblastic and neovascular changes associated with pterygium formation." (PMID 31976085, 2019). "In this study, we found a hypomethylated CpG unit located +484 and +602 bp downstream of MMP-2 transcription start site in pterygium." (PMID 21359202, 2011). "Recently, we demonstrated that MMP-2 and −9 are overexpressed in pterygium tissue and fibroblasts isolated from pterygium." (PMID 21224999, 2011). "In our study, we found that critical CpG islands associated with the MMP-2 and CD24 genes were demethylated in pterygium, whereas TGM-2 gene sequences were over-methylated." (PMID 21359202, 2011). "Elevated MMP-2 detected in pterygium has been shown to facilitate the invasive property of pterygium by degrading components of their basement membrane and adjacent stromal matrix." (PMID 21359202, 2011). "As such, MMP-2 and MMP-9 are tightly linked to the progression of pterygium in ocular diseases." (PMID 40565017, 2025). "Other MMPs, including MMP-2, -3, -7, -8, -9, and -14, are also present within pterygium tissue." (PMID 40565017, 2025). "Furthermore, MMP-2 and -9 are frequently detected at high levels in pterygium samples from human patients." (PMID 40565017, 2025). "MIR4435-2HG was co-expressed with FN1 and MMP2 and was highly expressed in pterygium." (PMID 33790949, 2021). "In addition, MMP-2 is the downstream gene of the β-catenin signaling pathway, and was uniquely expressed in pterygium epithelial cells." (PMID 21359202, 2011). "This raises the possibility that critical DNA demethylation may facilitate transcription factor(s) downstream of CSF2 to bind to regulatory sequences of CD24 and MMP-2, with a consequential increase in Wnt/β-catenin signaling, which has been previously reported in pterygium." (PMID 21359202, 2011). "By contrast, increased levels of MMP-2 and MMP-9 are observed in fibroblasts from pathologically advanced stages of pterygium." (PMID 40565017, 2025). "Lastly, oxidative stress is shown to promote metalloprotease-2 (MMP-2) activity and reduce tissue inhibitor of metalloproteases-1 (TIMP-1), which are events that significantly influence the growth of the pterygium." (PMID 38611627, 2024). "In fact, MMP-2 is specifically overexpressed in the epithelium and MMP-9 is abundant in pterygium vascular endothelium and inflammatory cells." (PMID 38611627, 2024). "In this study, multiple types of MMPs (MMP2, MMP3, MMP8, MMP9, MMP11, MMP16, and MMP28) were highly expressed in pterygium." (PMID 33790949, 2021). "A recent paper has shown that pterygium presents aberrant DNA methylation patterns in regions close to matrix remodelling genes such as TGM-2, MMP-2 and CD24." (PMID 22724003, 2012). "The methylation status at the promoters of TGM-2, MMP-2, and CD24 genes was significantly different between pterygium and uninvolved conjunctiva samples in at least one CpG unit." (PMID 21359202, 2011). "Immunofluorescent staining detected the presence of TGM-2, MMP-2, and CD24 in human conjunctiva and pterygium tissue." (PMID 21359202, 2011).
pterygium (continued). "MMP-2 and CD24 transcripts however, were upregulated 2.44±0.52 fold and 2.03±0.22 fold (p<0.05), respectively in pterygium compared to normal conjunctiva." (PMID 21359202, 2011). "Here, we report for the first time the role of methylation in the pathogenesis of pterygium, by profiling the methylation status of TGM-2, MMP-2, and CD24 gene promoters and the effect of methylation in cultured ocular surface cells." (PMID 21359202, 2011). "In this study, we demonstrate a significant increase in both MMP-2 and CD24 transcript and protein levels in pterygium tissue, with less methylation in the corresponding genomic sequences." (PMID 21359202, 2011). "We have previously investigated the genes specifically involved in wound healing mechanisms such as TGM-2, MMP-2, and CD24 in pterygium." (PMID 21359202, 2011). "Additionally, the co-expression of MMP-2 and MMP-9 is markedly enhanced in pterygium fibroblasts compared to normal fibroblasts." (PMID 40565017, 2025). "Besides our data, the literature reviews showed the aberrant DNA methylation and decreased expression of P16, Ecadherin, TGM 2, MMP2, and CD24 genes in pterygium." (PMID 26942001, 2016). "Methylation levels of TGM-2, MMP-2, and CD24 in pterygium and conjunctiva." (PMID 21359202, 2011). "TGM-2, MMP-2, and CD24 gene transcripts were detected in conjunctiva and pterygium tissues." (PMID 21359202, 2011). "Furthermore, through protein-protein interaction network and mRNA-lncRNA co-expression network analysis, key mRNAs including FN1, VCAM1, and MMP2, and key lncRNAs including MIR4435-2HG and LINC00968 were screened and might be involved in the pathogenesis of pterygium." (PMID 33790949, 2021). "Expressions of MMP-2 and MMP-9 are absent in early-stage pterygium and in cultured fibroblasts." (PMID 40565017, 2025).
tendinopathy (12 papers, 2011 to 2024). "In case of tendon disorders, there is an increase in the production of MMPs, in particular of MMP-2 during the acute phase, responsible for the degradation of the extracellular matrix and collagen." (PMID 39108992, 2024). "In regard to the expression of metalloprotease-encoding genes, increased expression of MMP2, MMP14, MMP16, ADAMTS2, ADAMTS3 as well as downregulation of MMP10 has also been found in tendinopathy." (PMID 38001919, 2023). "The gelatinase MMP2 was significantly upregulated in the tendinopathy and chronic rupture group compared to the intact and acute ruptured tendons, but MMP9 was not affected." (PMID 29385715, 2018). "MMP2 has also been shown to be upregulated in an animal model of tendinopathy and in tendinopathy patients." (PMID 25502628, 2014). "Although the exact pathway is unknown, we speculate that the NOX family, which has been previously reported to regulate the levels of various MMPs, may delay tendon healing by increasing the levels of tendinopathy-associated MMPs such as MMP9 and MMP2." (PMID 38247510, 2024). "Increased expression of Mmp2 and Mmp9 was not only seen in tendinopathy, but also during aging." (PMID 35008516, 2021). "In addition, a significant increase in the expression of Cox2, Mmp2, Mmp9, Col1a1, Col3a1, Vegf and Scx genes was also observed within the experimentally induced tendinopathy group compared with the control group." (PMID 33076550, 2020). "Previous research has indicated that TIMP-1 hinders excessive matrix degradation by impeding MMP activity, especially that of MMP-9, as MMP-2 and MMP-9 are upregulated in tendinopathies." (PMID 38247510, 2024). "MMP2, MMP3, MMP8, ADAMTS2, ADAMTS4, ADAM12 and collagen type I expression were regulated in a similar manner in tendinopathy compared to the current study." (PMID 23830915, 2013). "In addition to MMP-2 and MMP-9, MMP-3 has been found to be dysregulated during tendinopathies, which is inconsistent with its expected role in matrix remodeling." (PMID 38247510, 2024). "In contrast, MMP1 was upregulated in human patellar tendinopathy and increased expression of MMP1 was found in tendon ruptures Additionally, upregulation of MMP2 and MMP9 was shown to be a feature of tendinopathy and increased MMP9 activity was seen after exercise." (PMID 35008516, 2021).
viral infection (12 papers, 2013 to 2026). "MMP-2 is generally considered protective for the airways, however MMP-10 is induced by viral infections and is linked to increased submucosal thickness." (PMID 33718297, 2021). "Using levels of IL-6, LIGHT, and MMP-2, we differentiated viral infections correctly 95% of the time and CAP infection 54% of the time, yielding an overall accuracy of classification of 83%, a positive predictive power of 81.25%, and a negative predictive power of 83.33%." (PMID 41488910, 2025). "On the other hand, MMP-2 and MMP-9 play essential roles in placental ECM turnover during normal pregnancy; however, their dysregulation has been implicated in pathological processes such as preterm labor and vertical transmission of viral infections." (PMID 41465558, 2025). "Interestingly, has_circ_0078617 has previously been reported to regulate MMP2 expression as ceRNA during virus infection, revealing its potential immunomodulatory role." (PMID 36513974, 2022). "Hence, the current investigation has highlighted new knowledge of sivelestat as potent MMP-2, MMP-9, chikungunya nsP2 protease, and influenza neuraminidase inhibition activities, which help in the management of inflammation and viral infection-associated diseases." (PMID 38659558, 2024). "In the brain, activity of MMP2, MMP3, and MMP9 is induced under pathological conditions, including viral infection." (PMID 27303733, 2016). "The CXCL10/11high basal cells also had upregulated mRNA encoding for complement components (C1R and C1S), MHC class I (HLA-A, HLA-B, HLA-C, and B2M), and metalloproteases MMP2 and MMP13, the latter reducing repair during viral infection in bronchial epithelial cells." (PMID 40980495, 2025). "Both wt and E1A mutant virus infection of mice led to similar increases in the activity of two matrix metalloproteinases known to correlate with BBB disruption, MMP2 and MMP9, while causing no increase in the steady-state expression of MMP2 or MMP9 mRNA." (PMID 27303733, 2016). "In AE-COPD the gelatinolytic activity of MMP-2 was increased and furthermore, MMP-9 activation was significantly up-regulated irrespective of lung function, bacterial or viral infections and smoking." (PMID 26126526, 2015).